RAC2 (Rac family small GTPase 2)
Diseases named in the same sentence as RAC2 in open-access papers (continued):
Sharing a sentence is not in itself a finding about the gene and the disease.
thymus atrophy (1 paper, 2018). Acquired diminution of the size of the thymus associated with wasting as from death and reabsorbtion of cells, diminished cellular proliferation, decreased cellular volume, pressure, ischemia, malnutrition, reduced function or malfunction, or hormonal changes. "The role of Rac family in apoptosis was first suggested by thymus atrophy in mice expressing activated Rac2, a hematopoiesis-specific Rac family member, consistent with a Rac2-depedent apoptosis pathway in T lymphocytes." (PMID 29321004, 2018).
urticaria (1 paper, 2023). A vascular reaction of the skin characterized by erythema and wheal formation due to localized increase of vascular permeability. "The prevalence of urticaria was remarkably higher in patients carrying the RAC2 mutation, which is probably due to the defective mast cell functions in these patients." (PMID 37237458, 2023). "Among non-infectious atopic cutaneous complications, urticaria was highly prevalent among patients with congenital defects of phagocytes (p = 0.021), with both cases bearing RAC2 mutation." (PMID 37237458, 2023).
cancer (48 papers, 2013 to 2026). A tumor composed of atypical neoplastic, often pleomorphic cells that invade other tissues. "In cancer where overexpression of RAC2 is associated with poor prognosis, strictly targeting RAC2 can be a potential therapeutic strategy." (PMID 40072059, 2025). "Using expression data from 33 human cancers in large databases such as TCGA, RAC2 expression, survival, mutation, immune microenvironment, and enrichment analysis in various tumors can be explored." (PMID 37214785, 2023). "Our results showed a high expression of RAC2 in TME of many cancer types and were significantly positively associated with immunomodulators, immune checkpoint inhibitors, and immune cell infiltration." (PMID 37214785, 2023). "In particular, the T cell activation genes Rac2 and Igf1 were increased while the malignant tumor-associated genes Mgl2, Tnfrsf9, Vegfa as well as the M2 macrophage markers Retnla and Arg-1 were decreased." (PMID 37925462, 2023). "Although RAC2 is primarily expressed by hematopoietic stem and progenitor cells, recent reports have implicated RAC2 overexpression in the development and progression of malignant tumors of the brain, kidney, and lung." (PMID 34572445, 2021). "Our findings extend these studies: RAC2 is implicated in cancer cell migration and in its absence focal adhesions become static." (PMID 27531518, 2016). "Several molecular pathways are likely involved in the regulation of cancer stem cells (CSCs) via Ras-associated C3 botulinum toxin substrate 2, RAC2, and pituitary tumor-transforming gene 1 product, PTTG1, given their roles in cellular signaling, survival, proliferation, and metastasis." (PMID 40072059, 2025). "Furthermore, we examined the association between RAC2 genetic mutations and clinical survival outcomes in various cancers." (PMID 37214785, 2023). "In conclusion, RAC2 changes were characterized by “mutation” and “amplification” in most cancers." (PMID 37214785, 2023). "These outcomes indicated that low RAC2 expression may be associated with poor prognosis in 5 cancers; however, high RAC2 expression may be associated with poor prognosis in 6 cancers." (PMID 37214785, 2023). "RAC2 was diagnosed with the growth ofbrain cancer, but this gene may be linked with the development of EOC." (PMID 30970615, 2019). "This cascade causes RAC2 membrane localization and activation, inducing EMT to promote cancer metastasis and PNI." (PMID 41556039, 2026). "RAC2 is a promising target for cancer therapy, although its role seems context-dependent and requires further investigation." (PMID 40072059, 2025). "The contrasting roles of RAC2 in ccRCC and BC indicate the need for context-specific research to clarify the exact molecular mechanism by which RAC2 impacts tumor progression in different cancer types." (PMID 40072059, 2025). "Studies on prostate cancer cells proved that targeting the RAC2/PAK4/LIMK1/cofilin pathway impeded cancer progression and reinstated arsenic-induced cancer cell apoptosis." (PMID 40072059, 2025). "The roles of RAC2 and PTTG1 are critical in the molecular pathways underlying cancer biology, with both molecules contributing significantly to tumor initiation, progression, metastasis, and resistance to therapies." (PMID 40072059, 2025). "RAC2 appears to play an important role in mediating EMT in this type of cancer through its interaction with ADAM22 and the PI3K/Akt signaling pathway." (PMID 40072059, 2025). "This article aims to describe the molecular pathways involved in the proliferation, invasiveness, and drug response of cancer cells through RAC2 and PTTG1, aiming to clarify their respective roles in neoplastic process dependencies." (PMID 40072059, 2025).
cancer (continued). "All these genes interacting with RAC2 have been observed in a common pathway, that is, Wnt signaling pathway and pathways of cancer, when performed GO." (PMID 39233667, 2024). "This study explored the potential importance of RAC2 in the prognosis, immunotherapy, and cancer stem cell of 33 cancers, laying the foundation for mechanistic experiments and its future application in clinical practice." (PMID 37214785, 2023). "After a comprehensive analysis of the differences in RAC2 expression between tumor tissues and control tissues in databases such as TCGA and GTEx, the potential research significance of RAC2 in many cancers was identified." (PMID 37214785, 2023). "Firstly, the study of RAC2 expression in various cancers and its mechanism of action was incomplete." (PMID 37214785, 2023). "RAC2 had a strong relation with immune cell infiltration, immunomodulators, immunotherapy markers, cancer stem cell of THYM, and immune-related pathways." (PMID 37214785, 2023). "It was found that RAC2 expression had prognostic value in some cancers, for example, RAC2 affected the overall survival rate of ACC, BRCA, LAML, LGG, SKCM, THYM, and UVM." (PMID 37214785, 2023). "We further evaluated RAC2 expression in different cancers by supplementing normal tissues from the GTEx dataset, and 16 kinds of cancer were significantly increased in tumors with statistical differences." (PMID 37214785, 2023). "Previous studies limited RAC2 assessment on a few types of cancer, and the role of other tumor types remained elusive." (PMID 37214785, 2023). "RAC2 expression in ACC, KICH, KIRC, PAAD, SKCM, STAD, and THCA all showed a P < 0.05 and was associated with the pathological stage of the cancers." (PMID 37214785, 2023). "We found that compared with normal tissues, RAC2 expression was significantly elevated in most cancer tissues." (PMID 37214785, 2023). "Researches have been increasingly focused on analyzing the role of RAC2 in cancer, and much literature has demonstrated the important role of RAC2 in inhibiting the growth and metastasis of tumor." (PMID 37214785, 2023). "This was the first study focusing on the effect of RAC2 in pancancers and provided an innovative perspective on the role of RAC2 in cancer immunotherapy." (PMID 37214785, 2023). "The relationship between RAC2 gene expression and the prognosis of cancer patients was analyzed from OS, DSS, and PFI." (PMID 37214785, 2023). "Differentially expressed RAC2 between cancer and adjacent normal tissues was obtained from “Gene_DE” module of TIMER2." (PMID 37214785, 2023). "This salient observation that EHop-097 is a Vav/Rac specific inhibitor demonstrates its utility in inhibiting specific cancer cells, as well as immune cells, where the Vav1/Rac2 activation is central to immune cell function." (PMID 36861094, 2022). "It has been reported that the expression of APOBEC3D, TNFRSF14, and RAC2 is dysregulated and is a potential target for therapy in cancer." (PMID 36059808, 2022). "HNSCC cancer stem cell (CSC) marker CD44, integrin beta 4 (ITGB4), and small GTPase Rac2 were linked to the terms “Cell leading edge”, “Cell-substrate junction”, and “Focal adhesion”, while further genes showed linkages to one or two GO-terms." (PMID 36076232, 2022). "The cancer-upregulated exRNAs that were also most frequently detected among the cancer samples that came from RAC2, KRAS, and CAMK2A." (PMID 31481608, 2019). "Our previously published genomic and metabolomics results in cancer models suggested that Rac2-/- BMDMs are defective in M2 macrophage differentiation in vitro and in vivo." (PMID 28817691, 2017). "To conclude, PTTG1 and RAC2 are critical regulators of cancer progression and promising targets in anticancer therapy due to their roles in EMT, signaling pathways like TGF-β, PI3K/AKT, and NF-κB, as well as their influence on immune evasion and therapy resistance." (PMID 40072059, 2025).
cancer (continued). "Importantly, there is a relationship between altered RAC2 cellular levels and pathological stages of different types of cancers, which will be meticulously described in this article." (PMID 40072059, 2025). "RAC2 controls cytoskeleton reorganization, cancer cell migration, invasion, and EMT." (PMID 40072059, 2025). "This may also be an isoform dependent effect because cancer cells express Rac1 and Rac3, while hematopoietic cells express Rac2." (PMID 37397366, 2023). "CYBB, CYBA, NCF1, NCF2, and RAC2 are NADPH oxidase (NOX) subunit genes and are associated with inflammation and fibrosis in multiple organs, such as the liver, lungs, and kidneys, as well as with various types of cancer." (PMID 37109526, 2023). "As expected, RAC2 may be a biomarker of prognosis in many cancers; however, its prognosis varies across cancers, and these results should be further evaluated from multiple aspects." (PMID 37214785, 2023). "We also observed the relationship between RAC2 expression and cancer pathological stage." (PMID 37214785, 2023). "Unlike RAS proteins, which are frequently mutated in cancer (around 30%), RAC proteins (RAC1, RAC2 or RAC3) themselves are generally not found to be mutated in cancers at such a high frequency." (PMID 31027363, 2019). "In addition to the well-studied Rac1, we also report the importance of Rac2 and Rac3 in the regulation of cancer stemloids." (PMID 28160553, 2017). "However, studies have also shown that RAC2 also promotes cancer development." (PMID 37214785, 2023). "Rac2-KO and Rac3-KO mice showed slightly increased survival in a CML and ALL background, respectively, suggesting a possible oncogenic role for these genes; further experimentation will be required to determine the functional significance of these cancer-associated mutations." (PMID 27104658, 2016). "RAC2 and PTTG1 play significant roles in promoting EMT, which gives cancer cells stem-like properties and enhances their metastatic potential." (PMID 40072059, 2025). "While significant progress has been made in understanding the roles of RAC2 and PTTG1 in cancer biology, several knowledge gaps remain." (PMID 40072059, 2025). "Both RAC2 and PTTG1 contribute to the activation of the NF-κB and PI3K/AKT signaling pathways, which are essential for cancer cell survival, invasion, and therapy resistance." (PMID 40072059, 2025). "Protein-level analyses in nine cancer types revealed decreased expression of PLCB4, SOD3, and THRA, alongside increased expression of HMGB2 and RAC2, relative to normal tissues." (PMID 40852729, 2025). "The roles of RAC2 and PTTG1 in cancer biology underscore their potential as valuable prognostic markers and therapeutic targets." (PMID 40072059, 2025). "AFAP1-AS1 can indirectly influence activity of some cancer-related pathways such as EGFR/AKT, Wnt/β-catenin, PTEN/p-AKT, RhoA/Rac2 and PI3K/AKT." (PMID 34912717, 2021). "Considering age, several genes responsible for inflammatory protein secretion/activation (KLK3, EDN3), cell-adhesion (PI4KA, AHSAI1) and cancer-related proteins (KLK3, FGFR1/2, PRKACA, and RAC2) were also modulated in AYA-RMS." (PMID 31533233, 2019). "RAC2 also showed upregulation of proliferative pathways, including signalling by NTRK2/TRKB, characterised by overexpression of the PIK3CA gene, and signalling by ERBB2 in cancer, as reflected by elevated serum concentrations of SHC1, ERBB4, EGFR and ERBB2, compared with RAC3." (PMID 39401856, 2024). "Although direct molecular interactions between RAC2 and PTTG1 have not been conclusively established, existing evidence indicates that these proteins co-regulate critical cancer-related pathways, including epithelial–mesenchymal transition (EMT), immune evasion, and tumor progression." (PMID 40072059, 2025).
tumor (48 papers, 2009 to 2025). "In our study, integrated bioinformatics analysis indicated that low expression of NEDD4L and high expression of RAC2 were both associated with poor prognosis of ccRCC, pro-tumorigenic immunity, and multiple tumor-associated pathways." (PMID 39596003, 2024). "RAC2 was significantly positively associated with tumor stemness in THYM and negatively related with LGG, GBM, and KICH." (PMID 37214785, 2023). "From the perspective of immune invasion, we systematically associated RAC2 with immune characteristics in the tumor microenvironment (TME), including immunomodulators, immune checkpoint inhibitors, and tumor-infiltrating immune cells (TIICs)." (PMID 37214785, 2023). "Activating mutations of Rac2 have been shown to promote anchorage-independent growth as well as induction of tumour growth." (PMID 27531518, 2016). "Similar to previous reports, our study revealed that NEDD4L was downregulated and RAC2 was upregulated in ccRCC tissues, and low expression of NEDD4L and high expression of RAC2 were both associated with poor prognosis, shorter survival, higher tumor–node–metastasis stage, and worse G grade." (PMID 39596003, 2024). "RAC2 mRNA expression was increased in most tumor tissues and was associated with their prognosis." (PMID 37214785, 2023). "Notably, Rac2 is also implicated in tumor-induced angiogenesis, implying that the impact of Rac2 knockdown on tumor inhibition might involve both M1 macrophage polarization and the suppression of tumor angiogenesis." (PMID 38087370, 2023). "Nevertheless, there is limited understanding regarding the impact of RAC2 on autophagy within neoplasms." (PMID 40072059, 2025). "JNA, despite being a benign tumor, is characterized by its local expansion and destructiveness; therefore, this significant shift in RAC2 expression indicates its potentially diverse role in tumor development." (PMID 40072059, 2025). "Especially, RAC2 was predominantly related to NETs formation, thus providing hints towards anti‐tumour mechanism of NETs in OvCa." (PMID 39730971, 2024). "We concluded that RAC2 was upregulated (p‐value < 0.05) among individuals who suffered recurrence or tumour‐related death." (PMID 39730971, 2024). "This study preliminarily revealed the relationship of RAC2 in tumor immunity and explored its potential mechanism so as to provide a basis for further study of the relationship between RAC2 and tumor." (PMID 37214785, 2023). "While some genes such as GBP5 and RAC2 are predominantly expressed in immune cells (T cells and myeloid cells), other signature genes exhibited universal expression in both tumor cells and immune or stromal compartments." (PMID 37587913, 2023). "RAC2 was found to positively regulate tumor progression through controlling macrophage M1 to M2 differentiation and metastasis in the mice model." (PMID 33406731, 2021). "Rac2 knockout mice demonstrated a pronounced impairment in tumor growth, angiogenesis, and metastasis." (PMID 32603365, 2020). "As expected, at 3 dpf, neutrophil recruitment to the hindbrain was almost completely ablated in rac2 knockdown larvae, demonstrating efficacy of this model in preventing neutrophil migration to the site of tumor-initiation." (PMID 30185911, 2018). "In a recent study, we reported that Rac2-/- is required for tumor growth and M2 macrophage differentiation in tumor microenvironment." (PMID 28817691, 2017). "RAC2 controls macrophage differentiation from M1 to M2, which is well known to be important in tumor progression and the metastatic phenotype." (PMID 28029655, 2017). "In future studies, we will utilize our Rac2-/- model and other knockout and knockin models to pick-apart the pathways required for the provisional integrins to control tumor growth and metastasis." (PMID 24770346, 2014). "Taken together, these results suggest an important role for Rac2 in tumor growth, angiogenesis and invasion." (PMID 24770346, 2014).